VEGFA (vascular endothelial growth factor A)
Diseases named in the same sentence as VEGFA in open-access papers (continued):
Sharing a sentence is not in itself a finding about the gene and the disease.
cancer (continued). "Vascular endothelial growth factor A (VEGF) is a secreted factor that specifically acts on endothelial cells to stimulate angiogenesis making it a critical therapeutic target in cancers such as mRCC6." (PMID 27571927, 2016). "Vegf and TGFβ are important regulators of vasculogenesis and angiogenesis in both embryonic development and cancer progression, and crosstalk between them has been demonstrated, mainly through regulation of vegfA by TGFβ." (PMID 27499523, 2016). "Strikingly, methylation of the ESSE site was well correlated with VEGFA expression in the examined cancers." (PMID 26886256, 2016). "Of note, one of the genes strongly inhibited by DIG-MSK was VEGFA, which is a well-known Sp1-regulated gene in cancer." (PMID 26536461, 2015). "Hypoxia inducible factor 1, alpha subunit (HIF1A) was downregulated in common in cancer cells, while stromelysin-1 (matrix metallopeptidase 3), vascular endothelial growth factor A (VEGF-A), and neuropilin-1 were upregulated in common in fibroblasts." (PMID 26171396, 2015). "All these developmental processes occur via mechanisms similar to molecular cancer mechanisms, such as vascular endothelial growth factor A (VEGF-A)-stimulated angiogenesis." (PMID 26243145, 2015). "VEGFA, a cytokine that is a major regulator of angiogenesis in cancer is secreted by cancer cells under hypoxic conditions and leads to recruitment of endothelial cells through binding to its receptor." (PMID 24932473, 2014). "Microarray studies of two human cancer cell lines showed that tetrac and Nanotetrac downregulated expression of VEGFA, the gene product of which is a principal inducer of the porous blood vessels associated with cancers." (PMID 25628605, 2014). "Vascular endothelial growth factor-A (VEGF) is produced by most cancer cells as multiple isoforms, which display distinct biological activities." (PMID 25119572, 2014). "All the 3 family members of VEGFA, which are secreted by cancer cells, have the same target sequence so that all the VEGFA (referred to as VEGF, here) were depleted in the cancer cells." (PMID 25551022, 2014). "Our computer-based search for miR-205 targets also indicated that ErbB3 and VEGFA were cancer-related target genes of miR-205 in HuH28 cells." (PMID 24147037, 2013). "The VEGFA pathway often exerts powerful roles in regulating cancer-induced angiogenesis, which would have been missed in our human cell culture assays." (PMID 24009521, 2013). "Expression of VEGFA is known to have a pathological role when dysregulated, and its increased expression plays a role in the development of inflammation, edema, and cancer." (PMID 23903001, 2013). "Among stimuli responsible for the transcriptional up-regulation of the VEGFA gene, hypoxia has been of particular interest because of its role in cancer progression." (PMID 23851566, 2013). "In this study, the antipulmonary cancer effects of andrographolide were studied in a lung tumor mouse model induced by human vascular endothelial growth factor A165 (hVEGF-A165)." (PMID 23997793, 2013). "Subsequently, many other cancer cell lines were found to be inhibited in vivo by these antibodies and other anti-VEGFA treatments, including small-molecule inhibitors of VEGFR signaling, antisense oligonucleotides and antibodies to VEGFR-2." (PMID 23203097, 2012). "VEGFA is known to be upregulated in several forms of human cancer and is involved in multiple pathways including remodelling in normal and pathological conditions." (PMID 22593690, 2012). "Among these cancer biomarker candidates, TFRC, MET and VEGFA are commonly amplified genes in tumors and their encoded proteins stained positive in more than 80% of malignancies from public databases." (PMID 22761861, 2012). "Within the systemic circulation, VEGFA is consistently reported to increase in response to exposure to chronic hypoxia, while also being upregulated in cancer." (PMID 21266048, 2011).
cancer (continued). "In cancer cells, VEGFA induction mediated by the UPR is used to maintain abnormal ER homeostasis and help these cells to survive and proliferate under chronic ER stress conditions caused by nutrient deprivation and hypoxia." (PMID 20221394, 2010). "We focused our further analysis on VEGFA because it is the best characterized and most potent endothelial growth factor that promotes angiogenesis and is a target of cancer therapy." (PMID 20824063, 2010). "The regulation of SPHK1 by Runx2 probably potentiates additional aspects of the cancer phenotype, including angiogenesis (a function assisted by the Runx2 targets VEGFA and EDN2) and drug resistance." (PMID 20863401, 2010). "With the aim of creating a more effective tool for the diagnosis of cancer, we considered vascular endothelial growth factor A (VEGF-A) as a target marker protein." (PMID 20110884, 2010). "Here we report that the three master regulators of the UPR, IRE1α, PERK and ATF6α, mediate transcriptional regulation of VEGFA under ER stress which occurs during normal development of labyrinthine trophoblast cells in the placenta as well as in cancer cells." (PMID 20221394, 2010). "Vascular endothelial growth factor-A exists in most tissues, including cancer, as multiple isoforms generated by alternative splicing of a single gene product." (PMID 17595666, 2007). "In addition, cancer-associated fibroblasts (CAFs) can enhance VM formation in coordination with the ECM by secreting factors such as TGF-β1, FGF-2, and VEGFA." (PMID 41019994, 2025). "The inhibition of VEFGA results in the reduction of MAPK phosphorylation and the downregulation of the anti-apoptotic marker BCL-2, indicating that targeting VEGFA may represent a viable therapeutic option in the context of cancer." (PMID 40702566, 2025). "Considering that HCC is a malignant tumor rich in microvessels and that the VEGFA signaling pathway plays a key role, we hypothesized that ASH2L‐lys312 lactylation enhances angiogenesis, thereby facilitating HCC malignant progression." (PMID 40726441, 2025). "We conclude that anti-VEGFA and SU, at doses comparable to those used in cancer patients, may have anti-resorptive activity, though significantly less than that of an oncology dose of ZOL." (PMID 40177629, 2025). "The strong antitumor activity may be due to depletion of VEGFA in the TME upon BsAb-induced VEGFA co-phagocytosis with targeted cancer cells by the macrophages, compared with mainly sequestration of VEGFA by the action of the parental VEGFA antibodies." (PMID 40906526, 2025). "Although ICIs such as PD-1 blockers (e.g., pembrolizumab) and anti-VEGFA agents (e.g., bevacizumab) have revolutionized cancer treatment, their efficacy is often compromised by resistance mechanisms, including compensatory angiogenic pathways and immune evasion." (PMID 40607397, 2025). "Additionally, VEGFA initiates the epithelial-mesenchymal transition (EMT) process in cancer stem cells, thereby increasing their metastatic potential." (PMID 41268299, 2025). "Importantly, aberrant STAT3 signalling through pathways such as VEGFA not only drives tumour growth but also contributes to drug resistance by promoting a tumour-supportive microenvironment, enhancing cancer cell survival, and impairing therapeutic efficacy." (PMID 40407951, 2025). "Under these low-oxygen conditions, cancer cells release vascular endothelial growth factor A (VEGFA), which targets VEGF receptor 2 (VEGFR2) on adjacent endothelial cells (ECs) or on circulating endothelial progenitor cells derived from the bone marrow, thus initiating angiogenesis." (PMID 40313969, 2025).
cancer (continued). "As we and others have shown for ITGB3, VEGFA has been detected in cancer cell–derived EVs." (PMID 40662366, 2025). "Moreover, the hydrogel inhibited the invasiveness of cancer cells via the suppression of VEGFa and S100A6." (PMID 39852047, 2025). "Additionally, DBF4B showed a positive correlation with HMGB1, BTN3A1, and VEGFA across various cancers." (PMID 40535802, 2025). "Using a cell co-culture system, we found that VEGFA-EGFP signal was detected both in cancer cells (4T1-HLC cells) and in macrophages (RAW264.7) upon TG-VHS treatment, which supports our proposed working model in which VEGFA co-phagocytosis upon TG-VHS treatment occurs via a 2-step process." (PMID 40906526, 2025). "Additionally, VEGFA released by cancer cells exhibited strong interactions with the FLT1 receptor present on M1 macrophages and follicular centre B cells, while showing diminished affinity towards FLT1 on M2 macrophages." (PMID 40429821, 2025). "Moreover, treatment with HA extract alone and in combination with L-NAME led to significant downregulation of TNFa, VEGFa, COX-2, and MMP-2, which are key components associated with cancer progression and angiogenesis." (PMID 40179064, 2025). "Similarly, across various cancers, the expression of VEGFA by macrophages has been observed, further underscoring the significance of macrophages in the TIME." (PMID 41035074, 2025). "Notably, JNK inhibition partially reversed the stimulatory effect of MMP28 on IL-8 and VEGFA secretion by these cancer cells." (PMID 39972459, 2025). "Moreover, the VEGFA expression, a key pro-angiogenic factor in cancer cells, was markedly reduced in PAK1KD cells, suggesting a reduced angiogenic potential following PAK1 suppression." (PMID 41294859, 2025). "EV-miR-205-5p may be transferred from cancer cells to HLECs, thereby blocking the secretion of VEGFA and inhibiting lymphatic metastasis." (PMID 40302796, 2025). "In cancer cells or infiltrating immune cells, HIF-1a can recruit Treg by promoting CCL20, transforming growth factor-β (TGF-β), and vascular endothelial growth factor-A (VEGF-A), causing them to migrate to the TME." (PMID 39000453, 2024). "Besides that, few conclusions can be drawn after this, as the expression of VEGFA is related to a more complex mechanism dependent on other cellular types and their dynamics with cancer cells." (PMID 39125748, 2024). "Since the mTOR signaling pathway is reported to regulate VEGFA expression and promote ccRCC angiogenesis and progression, we tested whether the mTOR signaling pathway is one of the key pathways mediating the cancer-related function of RNF26." (PMID 38890443, 2024). "Furthermore, it has been revealed that miR-126 is downregulated in patients with BC and that it targets the VEGFA/PI3K axis to prevent the growth of cancer and angiogenesis." (PMID 38812786, 2024). "Under hypoxic conditions, cancer cells secrete vascular endothelial growth factor A (VEGFA) which binds to VEGF receptor 2 (VEGFR2) on nearby endothelial cells (ECs) of blood vessels or circulating bone marrow-derived endothelial progenitor cells, and triggering angiogenesis." (PMID 38602594, 2024). "Many TME-related genes (such as VEGFA, MMP14, CCND1, MAP2K1, SLC2A1) and actin cytoskeleton-associated genes (such as ITGB4, ITGA6, ACTG1, VCL) were downregulated, suggesting a less favorable TME and an altered cytoskeleton network in ISO-treated cancer cells." (PMID 38339062, 2024). "In summary, our study has demonstrated that canthin-6-one could be an alternative drug candidate for cancer to the current anti-angiogenic therapeutics which mainly targets the VEGFA/VEGFR2 pathway." (PMID 38256941, 2024). "However, increased expression of miR-29a hinders the spread of cancer cells to other parts of the body by targeting VEGFA, LOXL2, and LOX." (PMID 38915826, 2024). "In addition, small-molecule VEGFR2 inhibitors, initially described in 1996, have been explored to block the VEGFA-VEGFR pathway for cancer treatment." (PMID 38339258, 2024).
cancer (continued). "TAM-derived VEGFA may promote cancer stemness of TNBC through the NRP-1/GAPVD1/Wnt/β-catenin axis in an autocrine and paracrine manner." (PMID 38169627, 2024). "Therefore, enhancement of SCR in VEGFA will be useful to treat diseases with excessive and/or abnormal angiogenesis such as cancer and retinopathies." (PMID 38499809, 2024). "The excitement of molecular characterization of such a potent and clearly important factor led to many more questions, including whether VEGFA plays a role in other diseases that involve the vasculature besides cancer." (PMID 39087477, 2024). "Vascular endothelial growth factor A (VEGFA) is excessively expressed in cancers including GC; its involvement in GC development, particularly in multidrug resistance (MDR), and the signal route it affects in GC remain unknown." (PMID 39457390, 2024). "In addition to the combination therapy with tyrosine kinase inhibitor drugs, anti-VEGFA therapy can be combined with chemotherapy or immunotherapy in cancer treatment." (PMID 38687357, 2024). "The enriched pathways for downregulated genes in these same conditions uncovered TGFβ/Activin A signaling pathway, fibrosis, vascular endothelial growth factor A signaling, wound healing, autophagy pathways in cancer, proinflammatory/profibrotic mediators, nuclear factor-kB, and YAP1/ECM axis." (PMID 37739089, 2024). "Results of the experiments indicated that necroptosis could up-regulate VEGFA via the JAK2-STAT3 signaling pathway, thereby elucidating the potential mechanism underlying its role in cancer promotion." (PMID 39247606, 2024). "Likewise, HIF-1α also modulated epithelial-to-mesenchymal transition (EMT) through the VEGFA/NRP1 axis in low Gleason grade cancers." (PMID 36376373, 2023). "VEGFA is an important regulatory protein and plays key roles in cancer pathogenesis." (PMID 37234708, 2023). "However, we observed elevated immunoreactivity of VEGFA in ISUP 3 + 4 cancer tissues compared to control samples." (PMID 37964226, 2023). "Therefore, Serpin E1 derived from fibroblasts and subsequently cancer cells stimulates VEGFA expression through the p38 MAPK pathway in HUVECs, thereby contributing to GC development and progression." (PMID 38104099, 2023). "Moreover, multiple studies have shown that VEGFA positively regulates Wnt/β-catenin signaling through GSK-3β, which is associated with angiogenesis and cancer stemness in CRC, thus suggesting the potential autocrine action of VEGFA." (PMID 36672201, 2023). "VEGFA expression is high in various pathological conditions such as cancer and inflammation." (PMID 36672695, 2023). "The IL-6/STAT3/VEGFA signaling pathway is activated in different cancers." (PMID 36720310, 2023). "VEGFA and PGF levels were inversely associated with these scores in most cancers." (PMID 37852616, 2023). "For example, healthy dietary reduction in the expression level of VEGF-A (Vascular endothelial growth factor A) to combat cancer metastasis is a good example of our dietary strategy as opposed to only the use of a pharmaceutical drug such as which is expensive and sometimes toxic." (PMID 37305078, 2023). "Moreover, together with c-Jun, CDK6 upregulates the vascular endothelial growth factor A (VEGF-A) which is responsible for cancer progression and drug resistance due to its ability to induce angiogenesis." (PMID 37833875, 2023). "Although in the vast majority of KIRC samples an increased amount of VEGFA can be found, it is still uncertain whether the VEGFA expression pattern is related to the stage or grade of this cancer type." (PMID 37964226, 2023). "Thus, the low expression of VEGFA in PAAD tissues is consistent with the low vascular density characteristic of cancer tissues." (PMID 37822927, 2023). "VEGFA is a potent pro-angiogenic growth factor involved in cancer initiation and development." (PMID 38104099, 2023). "MYC in cancer could bind to the VEGFA promoter, thereby stimulating the VEGFA production and subsequently sprouting angiogenesis." (PMID 36966311, 2023).
cancer (continued). "As an inhibitor of FAS, orlistat has been reported to have anti-angiogenic activity, including regulating the production of total VEGFA in cancer cells, reducing the formation of capillary-like structures, and decreasing the number of metastatic cervical lymph nodes in BALB/c nude mice." (PMID 37601677, 2023). "VEGFA regulates most endothelial responses, modulates angiogenesis and participates in the pathogenesis of various angiogenesis-related diseases, including cancers." (PMID 37234708, 2023). "In the signaling pathway diagram, we found that OS may induce cancer cell apoptosis by inhibiting the VEGFA/HIF-1α pathway." (PMID 37713894, 2023). "VEGFA is the most characteristic regulator of angiogenesis and metastatic growth in human cancer." (PMID 38154103, 2023). "Therefore, the repressed VEGFA expression is often delivered as a therapeutic target for cancer angiogenesis." (PMID 38055382, 2023). "The combined use of circRNAs and VEGFA as cancer therapeutic targets might provide an opportunity for new forms of cancer treatment." (PMID 37234708, 2023). "Besides, a series publications reported similar researches, implanting human cancer cell lines into nude mice, and their results also proved the strong cross activities between human VEGFA and mouse endothelial cells." (PMID 36997943, 2023). "The VEGFA regulatory system is multifunctional and VEGFA is involved in cancer pathogenesis." (PMID 37234708, 2023). "Angiogenesis inhibitors, such as bevacizumab, a monoclonal antibody against vascular endothelial growth factor A (VEGF-A), are ineffective in reducing VM, which may contribute to drug resistance in cancer cells." (PMID 37351538, 2023). "The results indicated that sesamin could inhibit the angiogenic effect of VEGFA, prompting the therapeutic potential of sesamin in pathological conditions with increased angiogenesis such as cancer." (PMID 36672695, 2023). "Although both HSF-1 and HIF-1 are essential transcription factors for stress responses, a limited number of studies have reported that HSF family proteins, HSF2 and HSF4, promote transcription of HIF-1α and result in VEGFA expression in several cancer cell lines." (PMID 38081808, 2023). "The intensity of the VEGFA IHC reaction in cancer samples ranged from weak to strong." (PMID 37964226, 2023). "The top 1000 genes with decreased TE enriched in several cancer‐related pathways, including metabolism of RNA, translation, regulation of cellular response to stress and VEGFA–VEGFR signalling pathway, suggesting the role of NSUN2 in a crucial pro‐cancer program." (PMID 37983928, 2023). "Although VEGFA is upregulated in many tumors and is a target for many cancer therapies." (PMID 37822927, 2023). "Thanks to its ability to reduce angiogenesis by blocking VEGFA and HIF1α in IH, its high potential for use in cancer therapy is clearly indicated, since hypoxia and subsequent activation of the expression of HIF-dependent proteins play a vital role in cancer progression." (PMID 37446271, 2023). "The role of VEGFA in predicting mortality in a relatively healthy aging population is currently unclear; however, the role of VEGFA in both cardiovascular disease and cancer progression make it a plausible biomarker for predicting mortality due to these conditions." (PMID 37803875, 2023). "Moreover, we also detected several biomarkers of cancer proliferation and cell apoptosis such as VEGFA, EGFR and HIF-α, and the anti-apoptotic factor Bcl-2." (PMID 36855119, 2023). "VEGFA participates in tumorigenesis through different mechanisms, such as regulating angiogenesis and vascular permeability, affecting immune cell function, and modulating fibroblast function in the cancer stroma." (PMID 37234708, 2023). "Vascular endothelial growth factor-A (VEGFA) is an important factor affecting cancer pathogenesis." (PMID 37234708, 2023).